CDC5L (cell division cycle 5 like)
Description:
DNA-binding protein involved in cell cycle control. May act as a transcription activator. Plays a role in pre-mRNA splicing as core component of precatalytic, catalytic and postcatalytic spliceosomal complexes. Component of the PRP19-CDC5L complex that forms an integral part of the spliceosome and is required for activating pre-mRNA splicing. The PRP19-CDC5L complex may also play a role in the response to DNA damage (DDR). As a component of the minor spliceosome, involved in the splicing of U12-type introns in pre-mRNAs (Probable).
Synonyms: PCDC5RP; hCDC5; CEF1; CDC5; CDC5-LIKE; dJ319D22.1
Tractability: Small molecule: a structure with a bound ligand is known. PROTAC: UniProt records ubiquitination sites on it; ubiquitination databases record sites on it; its protein half-life has been measured.
Gene: Protein-coding gene on chromosome 6 (44,387,565 to 44,450,425, forward strand). Ensembl gene ENSG00000096401.
Subcellular location: Nucleus; Nucleus speckle; Cytoplasm
Subcellular location (Human Protein Atlas): Nucleoplasm
Pathways (Reactome):
Disease: Dengue Virus-Host Interactions
Metabolism of RNA: mRNA Splicing - Major Pathway
Gene Ontology:
Molecular function: DNA-binding transcription activator activity, RNA polymerase II-specific; identical protein binding; protein binding; RNA binding; RNA polymerase II transcription regulatory region sequence-specific DNA binding; WD40-repeat domain binding; DNA binding; DNA-binding transcription factor activity, RNA polymerase II-specific; protein domain specific binding
Biological process: DNA damage checkpoint signaling; mRNA splicing, via spliceosome; positive regulation of transcription by RNA polymerase II; regulation of transcription by RNA polymerase II; regulation of DNA-templated transcription
Cellular component: catalytic step 2 spliceosome; cytoplasm; DNA replication factor A complex; membrane; nuclear speck; nucleoplasm; nucleus; post-mRNA release spliceosomal complex; post-spliceosomal complex; Prp19 complex; spliceosomal complex; U12-type catalytic step 2 spliceosome; U2-type catalytic step 1 spliceosome; U2-type catalytic step 2 spliceosome
Genetic constraint (gnomAD): Loss-of-function variants: 10 observed, 65.12 expected, observed/expected ratio (o/e) 0.15, 90% interval 0.094 to 0.26. The upper end of that interval is the gene's LOEUF score, 0.26, which puts it in group 1 of 6, group 1 being the genes least tolerant of losing a copy. Missense variants: 487 observed, 685.76 expected, observed/expected ratio (o/e) 0.71, 90% interval 0.66 to 0.76. Synonymous variants: 215 observed, 234.84 expected, observed/expected ratio (o/e) 0.92, 90% interval 0.82 to 1.02.
Homologues: Orthologues: chimpanzee CDC5L (99% identical), macaque CDC5L (99% identical), rabbit CDC5L (99% identical), dog CDC5L (99% identical), guinea pig CDC5L (99% identical), pig CDC5L (99% identical), mouse Cdc5l (98% identical), mouse Cdc5lrt10 (96% identical), mouse Cdc5lrt7 (96% identical), rat Cdc5l (96% identical), mouse Cdc5lrt1 (96% identical), mouse Cdc5lrt4 (96% identical), and 8 more. Paralogues in human: MYBL1 (17% identical), MYBL2 (16% identical), MYB (16% identical), SNAPC4 (13% identical), DMTF1 (10% identical), TTF1 (6% identical).
Diseases named in the same sentence as CDC5L in open-access papers:
CDC5L is named in the same sentence as 52 diseases in open-access papers, as found by Europe PMC text mining. Sharing a sentence is not in itself a finding about the gene and the disease. The quoted sentences say what the papers report.
osteosarcoma (11 papers, 2010 to 2024). A usually aggressive malignant bone-forming mesenchymal neoplasm, predominantly affecting adolescents and young adults. "CDC5L was found to act as a candidate oncogene in osteosarcoma, cervical tumors, and bladder cancer." (PMID 34793589, 2021). "Overexpression of CDC5L has been detected in osteosarcoma patient samples and osteosarcoma cell lines alike, and is a probable candidate oncogene within the 6p12-p21 amplicon commonly found in osteosarcomas." (PMID 24835790, 2014). "Cell Division Cycle 5-Like (CDC5L), a regulator of the G2/M transition in the cell cycle, has demonstrated potential oncogenic activity in colorectal tumors, bladder cancer, cervical tumors, and osteosarcoma 39-42." (PMID 39668816, 2024). "Notably, CDC5L exhibits high expression levels in cervical tumors and osteosarcomas, underscoring its potential as a target for cancer therapy." (PMID 39209834, 2024). "Furthermore, the substantial overexpression of CDC5L in cervical tumors, bladder cancer, gliomas, and osteosarcomas emphasizes its critical role in the pathogenesis of these cancers and its potential as a therapeutic target." (PMID 39209834, 2024). "Interestingly, CDC5L has been related to other cancer types, such as prostate cancer and osteosarcoma." (PMID 37384253, 2023). "Recently, CDC5L was also found to act as a candidate oncogene in osteosarcoma and cervical tumours." (PMID 31897231, 2020). "We further demonstrated that exosomal RNAs including Annexin2, Smad2, MTAP, CIP4, PEDF, WWOX, Cdc5L, P27, could also discriminate good and poor chemotherapeutic response for osteosarcoma treatment." (PMID 29100284, 2017). "Similarly, CDC5L has been recently proposed as the putative oncogene at the 6p21 locus in osteosarcoma." (PMID 20465837, 2010). "However, CDC5L has been related to other cancer types, such as osteosarcoma and prostate cancer." (PMID 35453681, 2022).
bladder cancer (10 papers, 2020 to 2025). "CDC5L was highly expressed in bladder cancer and the expression of CDC5L was associated with multiple clinicopathological factors." (PMID 31897231, 2020). "The expression of CDC5L was significantly associated with bladder cancer pathology grade and Ki67 expression." (PMID 31897231, 2020). "Moreover, further study is needed to fully understand the underlying mechanism of CDC5L in the development of bladder cancer." (PMID 31897231, 2020). "Knockdown of CDC5L inhibited the proliferation of urothelial carcinoma cells by inducing apoptosis and limiting bladder cancer cell migration, invasion, and epithelial-mesenchymal transition." (PMID 41342186, 2025). "Previous studies have shown that CDC5L is highly expressed in tumors and involved in the occurrence and development of colorectal cancer, bladder cancer, breast cancer and other tumors." (PMID 40092703, 2025). "The expression of CDC5L in bladder cancer was shown to be obviously increased, and this increase is positively correlated with the pathology grade and the Ki67 expression level." (PMID 39534570, 2024). "Cell division cycle 5-like (CDC5L) protein, a cell phase regulator of the G2/M transition, has been demonstrated to improve bladder cancer cell proliferation, migration and invasion." (PMID 35814454, 2022). "Here, we found that CDC5L was highly expressed in bladder cancer and played an important role in the tumorigenesis of bladder cancer." (PMID 31897231, 2020). "We have further confirmed that CDC5L plays an important role in the metastasis of bladder cancer through the validation of clinical patient datas." (PMID 31897231, 2020). "The expression of CDC5L in fresh bladder cancer tissues and paraffin-embedded slices was evaluated by western blot and immunohistochemistry, respectively." (PMID 31897231, 2020). "Consistently, CDC5L expression was also higher in bladder cancer tissues than in the matched normal bladder tissues." (PMID 31897231, 2020). "The tumour tissues from the CDC5L knockdown group showed lower CDC5L expression levels and carried fewer Ki-67+ cells than in the control group, indicating a critical role for CDC5L in promoting bladder cancer growth in vivo." (PMID 31897231, 2020). "In bladder cancer, CDC5L expression was obviously increased and CDC5L expression was significantly related to pathology grade and Ki67 expression in bladder cancer." (PMID 32526706, 2020). "Consistently, we found that depletion of CDC5L in bladder cancer cells induced a decrease in AKT phosphorylation, but the total phosphorylation level did not change." (PMID 31897231, 2020). "Univariate and multivariate analyses showed that high CDC5L expression was an independent prognostic factor for the survival of bladder cancer patients." (PMID 31897231, 2020). "Taken together, the current data indicated that CDC5L promotes the growth of bladder cancer due to the inhibition of apoptosis." (PMID 31897231, 2020). "In addition, CDC5L is highly expressed in bladder cancer, and its expression is significantly related to the pathological grade of bladder cancer and Ki67 expression." (PMID 40092703, 2025). "A previous study has shown that CDC5L is a regulator of mitotic progression 15, and so we predicted that CDC5L might have effects on bladder cancer cell apoptosis." (PMID 31897231, 2020). "In summary, these findings suggest that CDC5L may play important roles in bladder cancer and we have confirmed that CDC5L contribute to the tumorigenesis of bladder cancer in vitro and in vivo." (PMID 31897231, 2020). "In addition, reduced expression of CDC5L induced apoptosis of bladder cancer cells and inhibited their migration, invasion and EMT." (PMID 31897231, 2020).
bladder cancer (continued). "The stained tissue microarrays indicated that CDC5L was highly expressed in 61.5% (40/65) of bladder cancer tissues compared with 38.5% (25/65) of the matched normal tissues and the high expression of CDC5L between bladder tumour tissues and matched normal tissues was statistically significant." (PMID 31897231, 2020). "In addition, we demonstrated for the first time that CDC5L has a significant effect on bladder cancer cell EMT, which closely relates to bladder cancer cell metastasis." (PMID 31897231, 2020). "Our results indicate that knockdown of CDC5L inhibits proliferation of bladder cancer cells." (PMID 31897231, 2020). "In this study, we demonstrated the expression and potential function of CDC5L in bladder cancer." (PMID 31897231, 2020). "Knockdown of CDC5L inhibited the growth of bladder cancer by promoting cell apoptosis." (PMID 31897231, 2020). "In this study, we investigated the effect of CDC5L on bladder cancer." (PMID 31897231, 2020). "Here, we analysed the expression and clinical significance of CDC5L in bladder cancer tissues." (PMID 31897231, 2020). "Therefore, our results suggest CDC5L contributes to promotion of EMT in bladder cancer progression." (PMID 31897231, 2020). "From these data, we infer that CDC5L might contribute to the progression of bladder cancer." (PMID 31897231, 2020). "Therefore, CDC5L may serve as a novel target for bladder cancer therapy in the future." (PMID 31897231, 2020). "However, the role of CDC5L expression in bladder cancer remains unclear." (PMID 31897231, 2020). "Furthermore, CDC5L inhibition suppressed proliferation, migration, invasion and EMT while induced apoptosis of bladder cancer cells." (PMID 32526706, 2020). "At present, there is no report on the role of CDC5L in bladder cancer and related mechanisms." (PMID 31897231, 2020).
colorectal cancer (6 papers, 2019 to 2025). A primary or metastatic malignant neoplasm that affects the colon or rectum. "Prp19/CDC5L is implicated in cell cycle regulation, mitotic checkpoint control, and DNA repair 7-10, linking it to cancer pathogenesis, as evidenced in non-small cell lung cancer, hepatocellular carcinoma, and colorectal cancer 11-14." (PMID 39990666, 2025). "The study aimed to explore the roles and interaction of DEAD-box helicase 21 (DDX21) and cell division cycle 5-like (CDC5L) in colorectal cancer (CRC) progression." (PMID 34903139, 2021). "Levels of DDX21 and CDC5L were detected in colorectal cancer cell lines by RT-qPCR and Western blot assay." (PMID 34903139, 2021). "CDC5L silencing inhibited the proliferation and migration of colorectal cancer cells and inhibited tumor formation in nude mice." (PMID 32167655, 2020). "The four candidate haplotypes harbor coding regions of several genes including CDC5L (cell division cycle 5 like), a positive regulator of cell cycle G2/M progression and key promoter of colorectal cancer cells." (PMID 30952955, 2019). "In vivo and in vitro experiments revealed that downregulation of DDX21 suppressed colorectal cancer cell proliferation, colony formation, cell cycle development, and tumor growth, while overexpression of CDC5L reversed the suppressive effects of DDX21 silencing." (PMID 34903139, 2021). "Li et al28 showed that CDC5L expression was high in colorectal cancer tissues and cell lines." (PMID 32167655, 2020). "CDC5L, known to be involved in various cancers, including non-small cell lung cancer, hepatocellular cancer, and colorectal cancer 11-14, was observed in our study to be associated with larger tumor volume, advanced T and N stages, and advanced pathological grades in GC." (PMID 39990666, 2025).
prostate carcinoma (5 papers, 2019 to 2023). A carcinoma that arises from epithelial cells of the prostate gland. "The oncogenic effects of NEAT1 have been reported to be influenced by the CDC5L-AGRN transcriptional regulation circuit in prostate cancer." (PMID 33428596, 2021).
hepatocellular carcinoma (4 papers, 2017 to 2025). A malignant tumor that arises from hepatocytes. "CDC5L was involved in the progression of hepatocellular carcinoma and was significantly associated with multiple clinicopathological factors." (PMID 31897231, 2020). "Studies indicated that CDC5L expression in glioma and hepatocellular carcinoma was increased, and CDC5L interference could increase the cell cycle arrest in G2 phase and inhibit the proliferation of glioma cells and hepatoma cells." (PMID 32526706, 2020).
multiple myeloma (4 papers, 2020 to 2025). "This study aimed to investigate whether annexin A7 (ANXA7) could promote the cell cycle, proliferation and cell adhesion-mediated drug resistance (CAM-DR) of multiple myeloma (MM) cells by up-regulating cell division cycle 5-like (CDC5L)." (PMID 32526706, 2020).
colon cancer (3 papers, 2019 to 2020). "Cell division cycle 5-like (Cdc5l) protein has been shown to promote hTERT expression and colorectal tumor growth, while metastasis biomarker Park7/DJ-1 is known to promote colon cancer by stimulating Wnt-β-catenin signaling." (PMID 32973493, 2020).
glioma (3 papers, 2020 to 2023). A benign or malignant brain and spinal cord tumor that arises from glial cells (astrocytes, oligodendrocytes, ependymal cells). "CDC5L expression is associated with tumor progression in glioma." (PMID 37579831, 2023). "Downregulation of CDC5L results in the apoptosis of glioma cells." (PMID 31897231, 2020).
lung cancer (3 papers, 2016 to 2025). A malignant neoplasm involving the lung. "RNA splicing is a major category of lung cancer vulnerabilities, as evidenced by the RNAi sensitivity patterns of the LSm2-8, 17S U2 snRNP and CDC5L complexes." (PMID 26755624, 2016).
Parkinson disease (3 papers, 2022 to 2025). A progressive degenerative disorder of the central nervous system characterized by loss of dopamine producing neurons in the substantia nigra and the presence of Lewy bodies in the substantia nigra and locus coeruleus. "Interestingly in module-4, we found CDC5L connected with FUS protein, which is one of the high-risk proteins of both familial and sporadic type ALS, Dementia, and Parkinson’s disease." (PMID 34918006, 2022).
breast carcinoma (2 papers, 2021 to 2025). "Because of the close relationship between CDC5L and the malignant process of breast cancer, we knocked down CDC5L in MCF-7 cells using siRNA." (PMID 40092703, 2025). "Analysis of the TCGA database showed that CDC5L was significantly overexpressed in breast cancer tissues compared with adjacent tissues, and patients with high CDC5L expression had poorer survival and prognosis." (PMID 40092703, 2025). "However, the specific mechanism of the relationship between EIF4A3 and CDC5L in breast cancer is still unclear and requires further clarification." (PMID 40092703, 2025). "In breast cancer, the phosphorylation inhibitor CVT-313 of CDC5L has high cytotoxicity in breast cancer cells." (PMID 40092703, 2025). "Correlation analysis with Glo1 expression gave the following: pan cancer—PPIL1, r = 0.59 and CDC5L, r = 0.58 (p < 1 × 10−6) and TRADD, r = −0.17 (p = 5 × 10−4); and for breast cancer—PPIL1, r = 0.55; CDC5L, r = 0.26 and TRADD, r = −0.20 (p < 1 × 10−6)." (PMID 34790575, 2021). "We propose that as an effector of EIF4A3, CDC5L is regulated by EIF4A3 and that EIF4A3 can bind to its mRNA, which in turn affects the expression of downstream CyclinD1 and promotes the proliferation of breast cancer cells." (PMID 40092703, 2025).
endometrial cancer (2 papers, 2023 to 2024). Primary or metastatic malignant neoplasm involving the endometrium (mucous membrane that lines the endometrial cavity). "For plasma proteins, a 4-marker panel combining CNDP1, CDC5L, APOD and PRDX6 had the least AIC value and predicted early-stage endometrial cancer with an AUC of 0.88 (0.82–0.95)." (PMID 38513301, 2024). "Cell division cycle 5-like protein (CDC5L) and Filaggrin (FLG) exhibited the largest fold changes, being sevenfold higher and lower in endometrial cancer compared to controls, respectively." (PMID 36807337, 2023).
melanoma (2 papers, 2017 to 2024). A malignant, usually aggressive tumor composed of atypical, neoplastic melanocytes. "Using bioinformatic, ChIP-PCR, and gene silencing analyses, we determined that cell division cycle 5-like protein (CDC5L) is an important transcription factor regulating FAH expression in melanoma cells." (PMID 29371990, 2017). "Our results indicate that FAH transcription, driven by cell division cycle 5-like protein (CDC5L), is essential in the metabolic reprogramming of melanoma by promoting important anaplerotic reactions that sustain tumor growth and potentiate the disease’s severity." (PMID 29371990, 2017). "To further confirm that CDC5L increases FAH expression, we knocked down the Cdc5l gene in melanoma cells using two siRNAs, and analyzed FAH expression by real-time RT-PCR and western blot." (PMID 29371990, 2017).